ALK (ALK receptor tyrosine kinase)
Diseases named in the same sentence as ALK in open-access papers (continued):
Sharing a sentence is not in itself a finding about the gene and the disease.
cancer (continued). "Gatekeeper or solvent front mutations frequently pose a liability for targeted kinase inhibitors, for example, ALK (ALKG1202R) and ROS1 (ROS1G2032R) recurrently arise in cancer patients treated with crizotinib, a type I ROS1/ALK/MET targeted TKI25,35,36." (PMID 33328556, 2020). "We collected 20 blood samples (AK01 to AK20) from NSCLC patients who were diagnosed as ALK-positive using FISH, IHC, and/or RT-PCR assays of cancer tissue biopsies." (PMID 31513617, 2019). "Similar to our findings in the ALK-inhibitor-resistant cells, PPP-induced downregulation of IGF-IR was shown to be pronounced in multidrug resistant cancer cells." (PMID 31340850, 2019). "Due to the approval of its application in ALK-positive NSCLC patients, these drugs will be increasingly used in routine cancer therapy as well as clinical trials." (PMID 30608384, 2019). "Lessons learned from studying molecular mechanisms of resistance to ABL, EGFR, ALK, KIT, and RAF inhibitors in human cancers have highlighted the need for next-generation kinase inhibitors that are effective against acquired secondary resistance mutations." (PMID 31371345, 2019). "Here, we report the safety, tolerability and recommended phase 2 dose (RP2D) of TSR-011 in patients with relapsed or refractory ALK- and TRK-positive advanced cancers." (PMID 31217479, 2019). "Antiproliferative activities of 1H-pyrazolo[3,4-b]pyridine derivatives against Ba/F3 transformed with ALK and H2228 NSCLC cancer cell." (PMID 31401883, 2019). "Our findings are applicable to other types of cancer where IGF-IR and ALK are simultaneously expressed." (PMID 31340850, 2019). "Different kinases such as anaplastic lymphoma kinase (ALK), Aurora kinase, RET receptor tyrosine kinase have been shown to be potential therapeutic targets in various cancers, including NB." (PMID 29416794, 2018). "With the identification of ALK as a common driver of NB in 2008, the results of early crizotinib trials in NSCLC provided the rationale for further evaluation in other ALK-driven cancers such as ALCL and ALK-positive NB." (PMID 29642598, 2018). "Since the discovery of ALK translocations in ALK-positive ALCL, a variety of mechanisms leading to aberrant/ectopic ALK signaling in several human cancers have been characterized." (PMID 29346274, 2018). "ALK inhibitors that were approved by the U.S. Food and Drug Administration (FDA) for specific cancers include ceritinib, crizotinib, alectinib, and brigatinib." (PMID 30400214, 2018). "Here, we found fusion genes involving BRAF, NTRK3, ALK, FGFR1, and ROS1, which result in activation of the MEK/ERK pathway in other cancers." (PMID 29654269, 2018). "ALK-TKI-resistant NSCLC cells with CSC properties and an acquired EMT phenotype have been noted to be responsible for cancer survival." (PMID 29930762, 2018). "Recently, two ALK-TKIs, crizotinib and ceritinib, have been approved for the treatment of advanced ALK-positive NSCLC patients, thus the use of these drugs is anticipated to be increased in anti-cancer treatment and clinical studies." (PMID 29507704, 2018). "Our findings are valuable for designing more specific and potent inhibitors for the treatment of ALK-positive NSCLC and other types of cancer." (PMID 28245558, 2017). "The ALK/GSK3β/β-catenin pathway is an impor-tant PTN-induced pathway that is involved in neural development and cancer progression." (PMID 28969035, 2017). "Our results provide valuable information for the design of more specific and effective treatment of ALK rearranged NSCLC and other types of cancer." (PMID 28245558, 2017). "We plated the established (pure cancer cell) cell lines of EGFR mutant or ALK-translocated NSCLCs into 384-well plates and compared their sensitivity to an EGFR or ALK inhibitor, respectively, using CellTiter-Glo or the immunofluorescence-based method." (PMID 29241554, 2017).
cancer (continued). "Although most clinical results regarding ALK inhibitors are from patients with ALK-positive non–small-cell lung carcinoma (NSCLC), it is clear from preclinical studies that ALK inhibition is effective in all ALK-expressing cancers." (PMID 29143801, 2017). "Despite a significant growth advantage for certain cancer cells in TCM, -E, -I media (MGH121-1 and MGH045-1), their response to EGFR or ALK inhibition was nearly identical to cells growing in R10 media." (PMID 29241554, 2017). "When combined with the ALK inhibitor, EGFR inhibitor gefitinib also showed an anti-cancer effect; however, the pan-HER inhibitor afatinib had a more potent effect on overcoming resistance, indicating the role of HER2 and HER3 activation in resistance." (PMID 28938595, 2017). "A recent trial of crizotinib in ALK-positive pediatric cancers demonstrated excellent activity in ALCL, where NPM-ALK is the major driver." (PMID 27483357, 2016). "Although the driver mutations including epidermal growth factor receptor (EGFR) and anaplastic lymphoma kinase (ALK) have revolutionized the treatment and prognosis of NSCLC, it just focused on the cancer cell intrinsic properties." (PMID 27153545, 2016). "We also summarize the ongoing and completed clinical trials validating ALK and ROS1 as targets for cancer treatment." (PMID 26802023, 2016). "They further found the resistance mechanisms to ALK TKIs mediated by both ALK and by a bypass signaling pathway mediated by EGFR, and these mechanisms can occur independently, or in the same cancer." (PMID 27386342, 2016). "Fusions involving the ALK, ETS and RET genes dominate this list, suggesting that updates to the treatment repertoires of the cancers affected by these fusions are forthcoming." (PMID 27105842, 2016). "Another interesting issue is the discordant distribution of signals among cancer cells between the FISH method and the Ventana IHC ALK(D5F3) method." (PMID 27418132, 2016). "Kinase fusion genes detected across multiple cancer types include RET, NTRK1, NTRK3, ALK, ROS1, FGFR1/2/3, and serine threonine kinases including the RAF family genes BRAF, RAF1, CRAF, and MAST1/2." (PMID 26684754, 2015). "First, drugs that inhibit ALK, ROS1, and RET kinases have marked therapeutic effects on fusion-positive LADCs because the survival and growth of such cancer cells are highly dependent on the kinase activity of fusion proteins." (PMID 26437441, 2015). "When pharmacological ablation of ALK oncogene was accompanied with PI3K inhibitor or salinomycin therapy, cancer stem-like cell features were reversed which was accompanied with decreased colony formation." (PMID 25238228, 2014). "Molecules such as Her2, EGFR, VEGFR, ALK, AKT, p52, cyclin D1, Met, Cdk4, HIF-1α or MMP2 which play important roles as oncogenes and are involved in essential pathways of cancer are described to be client proteins of HSP90." (PMID 24978439, 2014). "Two main bona fide cancer genes, MYCN and ALK, have been identified as major actors of NB pathogenesis." (PMID 24811913, 2014). "In ALK FISH-negative cases, the mean percentage of positive cancer cells was 0.7% (median 0%; range 0 to 6%)." (PMID 25248157, 2014). "Because genetic alterations in RTKs, such as FGFRs, EGFR, HER2, MET, ALK, and RET, drive human cancers, small-molecule inhibitors and human/humanized monoclonal antibodies targeted against RTKs have been developed as cancer therapeutics." (PMID 25364706, 2013). "To date, several more ALK hybrid proteins have been identified in various cancer types, such as TRK-fused gene (TFG)-ALK, tropomyosin 3 (TPM3)-ALK, tropomyosin 4 (TPM4)-ALK, clathrin heavy chain-like 1 (CLTCL1)-ALK, and moesin (MSN)-ALK." (PMID 23667670, 2013). "Both ALK and LTK play key roles in human cancers, whereas the ALK homolog in D. melanogaster directs gut and nervous system development and is associated with ethanol sensitivity and learning." (PMID 24379806, 2013).
cancer (continued). "ROS1 is a receptor tyrosine kinase that is closely related to ALK, and, like ALK, it undergoes genomic rearrangement that creates fusion proteins in NSCLC and other cancers." (PMID 24349229, 2013). "The threshold 0.318 was the scaled drug efficacy for crizotinib that inhibits ALK, which is the most essential kinase according to the siRNA screen and thus considered as effective in treating MCF7 cancer cells." (PMID 24068907, 2013). "ALK is activated by its ligands, midkine (MDK) and pleiotrophin (PTN), both of which serve as mitogenic and angiogenic factors in cancer." (PMID 24163262, 2013). "There have been development of inhibitors to some of the key intracellular molecules, kinases, e.g., MDM2 (murine double minute 2), ALK (anaplastic lymphoma kinase) and PARP (poly [ADP-ribose] polymerase) as anti-cancer therapeutics." (PMID 22475564, 2012). "The ERK pathway is activated in ALK+ ALCL cell lines and patient samples and plays a central role in promoting cell proliferation and suppressing apoptosis in this cancer." (PMID 22852078, 2012). "Previous investigations have shown that translocation of ALK can result in fusion with the neighbouring gene, EML4, in cancer cells." (PMID 20624322, 2010). "There was little cytotoxicity in the ALK‐negative cells, indicating that its cell‐killing activity was specific to cancer cells." (PMID 41362117, 2025). "Functional genetic studies have demonstrated that SHP2 is required for survival in RTK-driven cancer models, including those driven by oncogenic epidermal growth factor receptor (EGFR), anaplastic lymphoma kinase (ALK), and fibroblast growth factor receptor (FGFR) alterations." (PMID 40667115, 2025). "The efficacy and safety of alectinib for cancers with ALK-positive nonlung solid tumors have only been recorded in case reports." (PMID 40700600, 2025). "In our study, we analyzed the effects of lorlatinib, a different anti‐cancer drug targeting ROS1 and ALK, to determine whether ROS1 pathway can be an effective target for male contraceptives." (PMID 39568175, 2025). "Crizotinib is an anti‐cancer drug that inhibits both ROS1 and ALK (anaplastic lymphoma kinase)." (PMID 39568175, 2025). "A total of 1,501 distinct fusions in at least one of the nine driver genes assessed (ALK, RET, ROS1, NTRK1/2/3, FGFR2, FGFR3, and NRG1) were detected in 1,497 patients for a combined prevalence of 2.2% across the pan-cancer cohort." (PMID 41091579, 2025). "Additionally, HRi tumors demonstrated DEGs of kinase pathways including PI3K/AKT signaling in cancer (FE = 11.5, FDR = 8.88 × 10−3), ALK (FE = 22.7, P = 0.0276), and NTRK1 (FE = 8.1, P = 0.0330)." (PMID 40796942, 2025). "We here demonstrate the potential use of DBP to determine the cytotoxicity of ALK inhibitors and the anti-apoptotic programs involved in DTP cancer cell survival in ALK-rearranged NSCLC that we believe could impact its treatment in the future." (PMID 40113795, 2025). "Since ALK (EML4-ALK) and SRC play a role in other cancers, this approach may have broader relevance." (PMID 41154443, 2025). "Consequently, while ALK and ROS1 inhibitors have shown promise in other cancers, their applicability in iCCA remains limited due to the rarity of these genetic alterations." (PMID 41465387, 2025). "However, the combination of an ALK inhibitor with an anti-CD47 antibody yielded the greatest antitumor response, effectively eliminating all cancer cells from the culture." (PMID 38483480, 2024). "Moreover, numerous oncogenic drivers (ALK, BRAF, EGFR, MET, NRG1, NTRK1/2/3, RET, and ROS1) involved in sole reciprocal fusions were found in those cancers." (PMID 39254060, 2024). "Clinical trials are assessing new ROS1 inhibitors for ALK and ROS1 fusion-positive NSCLC cancers." (PMID 38655260, 2024). "The pan-cancer efficacy of repotrectinib was shown in the phase I/II registrational trial TRIDENT-1 (NCT03093116), which included patients with advanced solid tumors harboring ALK, ROS, or NTRK rearrangements." (PMID 39410015, 2024).
cancer (continued). "Low expression of thymidylate synthase may explain an increased sensitivity of ALK-, ROS1- and RET-driven cancers to pemetrexed." (PMID 38966170, 2024). "Currently undergoing clinical evaluation in ALK and ROS1 fusion-positive NSCLC cancers, PF-06463922, a next-generation ROS1/ALK small-molecule inhibitor, exhibits potent inhibition of various oncogenic ROS1 fusion variants and selective activity against a wide range of kinases." (PMID 38655260, 2024). "However, L1198F paradoxically enhances binding to first‐generation ALK‐TKI crizotinib, resensitizing resistant cancers to crizotinib." (PMID 39184861, 2024). "All ALK and ROS1 fusions were detected in adenocarcinomas, and RET fusions were detected mostly in adenocarcinomas (11/12, 91.7%), except in one case of poorly differentiated carcinoma." (PMID 39507756, 2024). "Evidence like this suggests that targeting ALK and SHP2 together might be a practical approach for treating cancer that has developed resistance to standard treatments." (PMID 38001644, 2023). "Therefore, we developed a novel approach to drug sensitivity test of ALK-targeted drugs using a CODRP index, which incorporates both PDO growth rate and cancer diagnosis stage in addition to AUC values." (PMID 37993887, 2023). "Selectivity was demonstrated by the finding that only ALK‐rearranged cancer cells, but not normal lung epithelial cells, showed sensitivity to ALK inhibitors (ALKi)." (PMID 36423211, 2023). "A total of 14,260 subjects were excluded due to absence of mNSCLC cancer, absence of systemic treatment received, or presence of EGFR mutation or ALK translocation." (PMID 37311845, 2023). "In oncogene-addicted cancers (HER2-mutant cancer, oncogene-driven EGFR-positive, ALK-positive, or RET-positive NSCLC), current studies do not encourage the use of immune checkpoint inhibitors, with the exception of KRAS-mutated cancers." (PMID 36865093, 2023). "Importantly, we also freshly raised cancer organoids which are reported as useful models for predicting patient‐specific drug responses, from a resected primary LUAD with ALK translocation (LUAD‐OG1)." (PMID 36709476, 2023). "In ALK‐rearranged primary cultures, the combined inhibition of ALK and PI3Kβ prevented the EGFR‐mediated ALK‐inhibitor resistance, and selectively targeted the cancer cells." (PMID 36423211, 2023). "Additionally, differences were observed in NR3C2, ATR, ALK, EPHB6, SPEN in intermediate cells (I-1 to I-8) relative to the cancer cells." (PMID 35951662, 2022). "Furthermore, MYCN mRNA levels were correlated with ALK expression, supporting the notion that ALK and MYCN cooperate in cancer progression." (PMID 36337169, 2022). "Our findings suggest that crizotinib-resistant metastatic NSCLC cells can develop cellular resilience mechanisms to resist molecular or cellular perturbation by inhibition of TGFβ signaling as well as ALK and MET, providing new insight into the mechanism of cancer drug resistance." (PMID 35999455, 2022). "In addition to ALK, RET, NTRK1, and ROS1, fusions involving FGFR1/2/3 and NRG1 genes have been reported in NSCLC among other cancers and represent emerging therapeutic targets." (PMID 35328282, 2022). "Currently, an increasing number of targeted therapies, including ALK, CDK and EGFR inhibitors combined with conventional radiotherapy and chemotherapy regimens are acknowledged as significant cancer treatment methods for individual therapy and to combat drug resistance." (PMID 35264157, 2022). "In conclusion, we characterized the genomic landscape of solid tumor patients with ALK, ROS1, and NTRK fusions and 62 novel fusions were discovered, which may provide more clinically actionable targets for cancer therapy to a great extent." (PMID 35785159, 2022). "Small molecule inhibitors for ALK, ROS1, and NTRK fusions, such as crizotinib, brigatinib, lorlatinib, entrectinib and larotrectinib, have been approved by the US Food and Drug Administration (FDA) for different cancer types." (PMID 35785159, 2022).
cancer (continued). "Mutant ALK upregulates the expression of PD-L1, which may potentially confer an immunosuppressive TME, contributing to tolerance and immune evasion in cancer." (PMID 35958559, 2022). "Case #14 related to a combined carcinoma with dubious ALK expression was negative with both the Idylla and FISH approaches." (PMID 36612287, 2022). "Taken together, we hypothesize that increased autophagic flux induced by adverse conditions promotes cancer stemness and a high protein level of MYC in ALK+ ALCL." (PMID 34685497, 2021). "We hypothesised that ALK-driven NB, which often involves MYCN amplification, may also represent a situation where cancer cells are more dependent on the integrity of ATR-regulated checkpoint responses and therefore sensitive to ATR inhibitors." (PMID 34819497, 2021). "Future scrutiny will also involve CPI combination with TKI in never smoking molecular subsets beyond EGFR and ALK positive cancers, including those with BRAF V600, RET fusion and MET exon 14 who have shown promising TKI efficacy." (PMID 32915318, 2021). "Similarly, mouse models of MYC-rearranged B-cell lymphoma and ALK-rearranged NSCLC displayed highly penetrant phenotypes, precluding the study of the stochastic events driving cancer growth." (PMID 34585724, 2021). "Anaplastic lymphoma kinase (ALK), a member of the insulin receptor tyrosine kinase family, has been identified as a fusion partner of nearly 30 different proteins in oncogenic signaling in many different cancer types." (PMID 34926258, 2021). "Similar to other oncogenic RTKs, like EGFR and ALK, distinct FGFR mutants might harbour different signalling dependencies, driving cancer progression by the activation of altered downstream pathways." (PMID 34068816, 2021). "OS was better for ALK‐positive patients compared with ALK‐negative patients, The 3‐year cancer‐specific survival rates were 89.1 ± 3.7% versus 80.9 ± 2.3%, respectively (p = 0.037)." (PMID 34596344, 2021). "In addition, kinases are ideal targets for cancer therapy; several inhibitors against kinases, such as ALK and BRAF, have been used to treat cancers with fused genes." (PMID 33557176, 2021). "It is known that Oct4 is overexpressed in many types of cancers, although this protein has not been previously studied in ALK + ALCL." (PMID 34287231, 2021). "Indeed, several studies have demonstrated that SHP2 inhibition can overcome resistance to EGFR, HER2, ALK, and MEK inhibitors in multiple cancer models." (PMID 34503119, 2021). "AXL/ALK/FLT3 inhibitors (e.g., gilteritinib) have shown promise as anti-cancer agents." (PMID 33917370, 2021). "It has been observed for many years, in many studies, that ALK+ ALCL has characteristically low expression levels of B-cell Lymphoma 2 (BCL2) proteins, whereas BCL2 overexpression is a classical feature of cancers, including hematopoietic tumors." (PMID 34685497, 2021). "Moreover, the kinase inhibitor crizotinib was specifically designed to inhibit ALK and c-MET (hepatocyte growth factor receptor, HGFR) and is currently being clinically investigated in several cancer indications." (PMID 33953226, 2021). "This might weaken their efficacy against brain tumors (e.g., brain metastasis and gliomas) that often also include ROS1, ALK, and NTRK fusion-positive cancers." (PMID 34834176, 2021). "After surgery, the patient was referred to our cancer center, where a review of the histology slides gave a final diagnosis of ALK-negative lung IMT." (PMID 34011083, 2021). "Although acquired ALK mutations remain an important resistance mechanism to ALK inhibitors currently guiding therapeutic decisions, heterogeneous ALK-independent signaling and non-mutation-driven pathways may equally influence cancer progression and treatment resistance." (PMID 34272470, 2021). "Furthermore, ALK chimeric antigen receptor (CAR-T) therapy and vaccines are currently under development for ALK-altered cancers." (PMID 32059449, 2020).